TLR4 (toll like receptor 4)
Diseases named in the same sentence as TLR4 in open-access papers (continued):
Sharing a sentence is not in itself a finding about the gene and the disease.
Sepsis (continued). "In comparison to the sham group, the sepsis group had significantly higher levels of TLR-4, IL-6, TNF-α, MIF, F2-isoprostane, caspase-3, cTn-I, and CK-MB, while the pre-treated group with Xanthohumol had significantly lower levels (p<0.05) of these markers than the sepsis group." (PMID 37900069, 2023). "This pathway, in which endotoxin is recognized by TLR4 of macrophages, monocytes, neutrophils and tissue cells such as hepatocytes, endothelial cells, etc., has been described as responsible for the pathophysiology of sepsis." (PMID 37875957, 2023). "The progress in research on LPS recognition systems, witnessed in the last decade, led to important discoveries of TLR4-independent LPS-sensing pathways that may have a central role in the pathophysiology of sepsis and related mortality." (PMID 35160068, 2022). "TLR4-mediated MyD88/NF-κB signaling way is the key pathway in sepsis pathophysiology." (PMID 35722155, 2022). "Furthermore, sepsis activates the TLR4 pathway to promote macrophage infiltration, thereby impeding neuromuscular function." (PMID 35464001, 2022). "Our results suggest that alleviation of sepsis may correlate with the downregulation of levels of TLR4, NF-κB, and MyD88." (PMID 35722155, 2022). "It has been revealed that Siglec-9 helps endocytosis of toll-like receptor 4, regulates macrophages polarization, and inhibits the function of neutrophils by mediating death signals in neutrophils during infection in the pathogenesis of sepsis." (PMID 35844622, 2022). "LncRNA SNHG5 relieves sepsis-induced AKI by regulating the miR-374a-3p/TLR4 axis." (PMID 35510365, 2022). "Therefore, the discovery of approved drugs to modulate TLR4 activity would be a cost-effective and practical way to cure sepsis." (PMID 35281916, 2022). "Therefore, in this study, a model of sepsis induced by LPS was constructed to explore the effects of EA at ST36 on TLR4 signaling and the intestinal flora." (PMID 35722155, 2022). "For instance, it has been found that Asp299Gly and Thr399lle SNPs of TLR4 are associated with an increased risk of gram-negative bacterial infections and sepsis." (PMID 35986268, 2022). "The initial inflammatory response is mainly activated by pattern recognition receptors, where Toll-like receptor 4 (TLR4) activation is one of the key receptors associated with Gram-negative bacterial infections commonly producing sepsis." (PMID 36261775, 2022). "TLR4 is involved in immune cell activation and mediates brain injury by activating neutrophils, T-lymphocytes, and NK cells in the pathogenesis of stroke and sepsis." (PMID 34975308, 2022). "It has been shown that in sepsis, inflammatory mediators originating from pathogens and activated immune cells can act on renal tubular epithelial cells via a Toll-like receptor 4 (TLR4)-dependent pathway, leading to mitochondrial dysfunction and tubular epithelial cell injury." (PMID 35859295, 2022). "Let-7b can potentially enhance the synthesis of inflammatory cytokines, activating TLR4/NF-κB pathway and inhibiting the TLR4 expression, which in COVID-19 patients may be interesting especially in neutrophils, due to their role in sepsis development." (PMID 35938548, 2022). "During sepsis, PAMPs could bind to the corresponding receptors on the surface of astrocytes, such as TLR4, activate the NLRP3 inflammasome to induce pyroptosis, and release histones to damage neurons." (PMID 36062193, 2022). "Excessive stimulation of TLR4 by lipopolysaccharide (LPS) not only enhances macrophage phagocytosis of bacteria, but also induces overwhelming proinflammatory cytokines production which can lead to multiple organ failure and death of sepsis." (PMID 35370674, 2022). "By integrating prior knowledge from literature using mathematical modelling techniques, we aimed to obtain a deeper mechanistic insight into sepsis pathogenesis and to evaluate promising novel therapeutic targets, with a focus on Toll-like receptor 4 (TLR4)-mediated pathways." (PMID 36261775, 2022).
Sepsis (continued). "However, Non-infectious factors can also induced gut epithelial barrier dysfunction and subsequent bacteria translocation even sepsis of gut origin are mediated by TLR4 signaling." (PMID 36088483, 2022). "Furthermore, the therapeutic potential of strategies aiming to restrain the function of TLR4 to repair the intestine function of sepsis requires further validation." (PMID 36088483, 2022). "For example, RNF115 negatively regulates TLRs-mediated signaling and autoimmunity and targeting RNF115 might promote TLR4-related sepsis or TLR7/9-related autoimmunity." (PMID 35844553, 2022). "In addition, our prior research also verified that TRIM7 can regulate the expression of inflammatory factors after infection through TLR4 pathway, which makes it an important molecular in the development of sepsis." (PMID 36402943, 2022). "TLR4-mediated inflammation, triggered by DAMPs, is involved in several diseases such as sepsis." (PMID 35762086, 2022). "TLR4 has long been proposed to be a promising target for immune-modulative sepsis therapy." (PMID 36230982, 2022). "Toll-like receptor 4 (TLR4) is a key target in the pathophysiology of sepsis." (PMID 35722155, 2022). "LNT regulates sepsis via the TLR4/MyD88 signaling pathway, according to previous research." (PMID 35669119, 2022). "TLR4 responds to LPS facilitating elimination of invading bacteria during infection, but also immediately triggers exaggerated pro-inflammatory responses even leading to sepsis or death." (PMID 35370674, 2022). "EGFR phosphorylation is required for TLR4-mediated macrophage activation during sepsis." (PMID 36344490, 2022). "We speculated that remifentanil might alleviated the sepsis-induced kidney injury through TLR4/NF-κB signaling pathway." (PMID 36263441, 2022). "Blocking the C-terminal CaM/IP3R binding domain in TRPC with chemical inhibitor could obstruct the Ca2+ leak and TLR4-mediated inflammation burst, demonstrating a cardioprotective effect in endotoxemia and polymicrobial sepsis." (PMID 36460692, 2022). "Similarly, models utilizing mice deficient in AIM2, TLR9, TLR4, IRF3, and related proteins were protected in experimental sepsis models, suggesting further therapeutic potential." (PMID 35961978, 2022). "Our study suggests that circSTRN3 upregulation in sepsis-induced AKI regulates miR-578/TLR4 axis to aggravate AKI, which could serve as potential therapeutic targets for AKI treatment." (PMID 35510365, 2022). "Sepsis could activate Toll-like receptor 4/nuclear factor-k-gene binding (TLR4/NF-kB) pathway to change the structure and function of TJ." (PMID 36062193, 2022). "In addition, in a neonatal mouse model of sepsis, the use of immunomodulatory agents, including Toll like receptor 4 (TLR4) or TLR7/8 agonists, aluminum salt-based adjuvants, and Bacille Calmette-Guérin (BCG), have been investigated extensively." (PMID 34945120, 2021). "After TLR4 inhibition, pyroptosis may become an important type of cell death in stimulated PBMCs in patients with sepsis." (PMID 34733114, 2021). "Impaired monocyte phagocytic activity and defective TLR4 expression in the CD14+highCD16− and CD14+highCD16+ monocyte subsets might be involved in common causes, predominantly septicemia, of death in the years following SCI." (PMID 33451043, 2021). "Since annexin A5 inhibits HMGB-1 interaction with TLR4 in models of sepsis and inflammation, it could interfere with HMGB1-mediated SARS-CoV-2 infection." (PMID 34566657, 2021). "Also, activation of TLR4 has been detected as part of the inflammatory response in patients with liver injury induced by sepsis." (PMID 33369167, 2021). "Herein, we investigate the hypothesis that the TLR4/ERK1/2/KLF4/ITGA2B axis mediates the inflammatory response of sepsis." (PMID 33369167, 2021). "However, it is important to keep in mind that TLR4 activation and its consequent pro-inflammatory response is necessary for bacterial elimination during sepsis." (PMID 33467524, 2021).
Sepsis (continued). "And in this study, we observed severe pyroptosis and serious damage of the liver in septicemia-related liver injury in CD38-deficient mice, whereas both pyroptosis and damage of the liver can be significantly reversed in TLR4 mutant mice, accompanied by the decrease in NLRP3 and GSDMD." (PMID 33860064, 2021). "During the current investigation, we aimed to prove the hypothesis that the TLR4/ERK1/2/KLF4/ITGA2B axis is capable of mediating inflammatory response of sepsis." (PMID 33369167, 2021). "One of the possibilities might be that cell death in CD4 lymphocytes in patients with sepsis was mainly via apoptosis since TLR4 inhibition could elevate the Bcl2 to Bax ratio to suppress apoptosis." (PMID 34733114, 2021). "MD-2 is co-expressed with TLR4 on the cell membrane of various cell types including leukocytes and endothelium, but soluble MD-2 (sMD-2) is elevated in plasma from patients with inflammatory conditions, such as sepsis, HIV infection, and endotoxemia." (PMID 33841413, 2021). "In sepsis, bacterial LPS can also activate platelets via TLR-4 to shed PMPs." (PMID 34831457, 2021). "Another lncRNA that participates in sepsis via TLR4 signaling pathway is acidic protein/four-disulfide core domain 21 (Wfdc21), also known as lncRNA DC, whose expression level was elevated in the cecal ligation and perforation (CLP)-induced animal model as well as LPS-induced macrophages." (PMID 34055659, 2021). "To test this hypothesis, we established CLP‐induced septic mice and LPS‐induced RAW264.7 cells and characterized the role of the TLR4/ERK1/2/KLF4/ITGA2B axis in the setting of sepsis in vivo and in vitro." (PMID 33369167, 2021). "However, overexpression and abnormal activation of TLR4 leads to chronic and acute inflammatory disorders such as endotoxemia and sepsis in human and equine." (PMID 34733317, 2021). "D+L group could significantly increase the level of Cav-1 protein and decrease the level of TLR-4 and NLRP3 protein in liver tissue caused by sepsis." (PMID 33558888, 2021). "Moreover, TLR4 knock‐down or treatment with PD98059 (a MEK inhibitor) inhibited inflammatory response in the setting of sepsis in vivo and in vitro." (PMID 33369167, 2021). "The network constructed for comparing patients with sepsis to patients with COVID-19 ARDS also suggested an upregulation of several key molecules relevant for the pathogenesis of COVID-19 ARDS which included TLR4, IL6, and - in particular - STAT1 (signal transducer and activator of transcription 1)." (PMID 34956213, 2021). "Our results suggest that miR-let-7b could regulate immunosuppression by targeting the neutrophilic TLR4/NF-κB signal during CLP-induced sepsis." (PMID 33868293, 2021). "Although TLR4 plays an important role in sepsis, it can also be activated by LPS." (PMID 34421582, 2021). "Inhibition of TLR4 can improve the prognosis of sepsis, so TLR4 blockers may be used as a potential new method for the treatment of sepsis." (PMID 33816356, 2021). "Similarly, knockdown lncRNA TapSAKI alleviated kidney injury in urine-derived sepsis rat model by targeting the miR-22/PTEN/TLR4/NF-κB signaling pathway through ceRNA mechanism." (PMID 34055659, 2021). "Moreover, renal resident cells also expressed TLR, in particular TLR2 and TLR4, and actively participate in sepsis-induced AKI." (PMID 33868226, 2021). "We confirmed experimentally that lentinan could significantly reduce the protein expression of NF-κB as well as TLR4, NF-κB, and Bax, but increase the expression of occludin and Bcl-2 in intestinal tissue of mice with gut-origin sepsis." (PMID 34790828, 2021). "One study has reported that the expression of TNF-α was downregulated in Irak1-deficient macrophages when TLR2 or TLR4 were activated, thereby weakening the response to the lethal effects of sepsis caused by LPS or Gram-negative bacteria." (PMID 34421892, 2021).
Sepsis (continued). "The modulation of pro-inflammatory responses via the TLR4 signaling pathway was found beneficial for management of acute and chronic inflammatory disorders including asthma, allergy, arthritis, Alzheimer disease pathology, sepsis, and cancer." (PMID 33815382, 2021). "Accordingly, we investigated further the role of the TLR4/ERK1/2/KLF4/ITGA2B axis in sepsis." (PMID 33369167, 2021). "In addition to the TLR4 pathway, lncRNAs can affect the hyperinflammatory state in sepsis via other pathways." (PMID 34055659, 2021). "Therefore, examining the function and mechanism of TLR4/TRAF6 in LPS-induced myocardial injury is expected to reveal a novel therapeutic approach for sepsis-induced myocardial injury." (PMID 34489703, 2021). "The underlying mechanism is that dexmetomidine may up-regulate the expression of Cav-1 down-regulated by sepsis, which may conduce to the suppression of TLR-4/NLRP3-mediated signaling pathway, at least in part." (PMID 33558888, 2021). "However, the expression levels of TLR4 on platelets during sepsis are discussed in studies showing unaltered TLR expression on platelets from sepsis patients, while others describe increased TLR4 expression on sepsis platelets." (PMID 34360659, 2021). "A direct antagonist anti-TLR4 monoclonal antibody has been developed to treat rheumatoid arthritis and may be a worthwhile target for further investigation in those with sepsis." (PMID 33803628, 2021). "This is of particular importance because platelet TLR4 is probably involved in the thrombotic response of platelets to sepsis, even independently of MyD88 signaling, and platelet TLR4 signaling may use other pathways, including TRIF." (PMID 34360659, 2021). "Our results suggested that Linc-KIAA1737–2 could promote LPS-induced apoptosis in HK-2 cells, and presumably sepsis-induced acute kidney injury, by regulating the miR-27a-3p/TLR4/NF-κB axis." (PMID 34076840, 2021). "Subsequently, excessive expression of TLR4 caused over-activation of NF-κB and increased release of inflammatory mediators such as TNF-α, IL-6, and IL-8, which can cause tissue injury and even sepsis." (PMID 34712822, 2021). "Importantly, literature reveals that lncRNA MALAT1 can relieve the symptoms of sepsis-induced acute lung injury via TLR4/NF-κB and p38 MAPK signaling pathways." (PMID 34516310, 2021). "As a ligand of LPS, TLR4 can prevent the cascade of inflammation by intervening in the early stage of sepsis, but its complete blockade may also lose the body’s innate immune response to endotoxin." (PMID 33816356, 2021). "Notably, TLR4 activity has the potential to exert suppressive effects on immune dysfunction in sepsis." (PMID 33369167, 2021). "After TLR4 inhibition, there was an unknown mechanism to keep cell death in stimulated PBMCs in patients with sepsis." (PMID 34733114, 2021). "The activation of innate immune receptors by fungi generally follows the same pattern as bacteria, with TLR2, TLR4, TLR9 and NLRP3 being common to the fungi (Aspergillus, Candida and Cryptococcus species) most often associated with COVID-19, ALI/ARDS and sepsis." (PMID 33672738, 2021). "Schisandrin B attenuates LPS-induced sepsis in mice by down-regulating TLR4 via miR-17-5p." (PMID 34705665, 2021). "Furthermore, TLR4/NF-κB signaling has been shown to play a role in promoting sepsis-induced cardiac dysfunction." (PMID 34787054, 2021). "Since platelets express TLR4 and bind to neutrophils in the capillaries of lung and liver upon sepsis, it is tempting to speculate that soluble biglycan is able to bind to platelet TLR4 to mediate platelet-induced inflammatory responses." (PMID 34830059, 2021). "The TLR4 pathway is also a classical pathway for inducing inflammatory signaling in cells and plays an important role in the activation of inflammatory reactions and immunomodulation in sepsis." (PMID 32952953, 2020).
Sepsis (continued). "Another pertinent point is that C3H/HeJ mice with non-functional mutation in TLR4 had normal cytokine response and organ injury indistinguishable from WT mice in response to polymicrobial sepsis." (PMID 33336149, 2020). "We further investigated whether sesamin can similarly alleviate LPS-induced sepsis in vitro through the HMGB1/TLR-4/IL-33 pathway." (PMID 32893702, 2020). "Another TLR4 antagonist, eritoran, also failed in clinical studies of severe sepsis." (PMID 31973752, 2020). "Anti-TLR4 therapy has been regarded as promising avenue for sepsis." (PMID 32099901, 2020). "Moreover, it was demonstrated that TLR4 exhaustion contributed to resistance in immune dysfunction induced by sepsis." (PMID 32099901, 2020). "TLR4, a member of the Toll-like receptor family of transmembrane proteins, recognizes pathogens, such as LPS, and is responsible for the inflammatory cascade in sepsis." (PMID 32685466, 2020). "Therefore, sesamin pre-treatment effectively attenuated the HMGB1/TLR-4/IL-33 signalling pathway, which was enhanced by sepsis." (PMID 32893702, 2020). "Taken together, these observations suggest that systemic inflammatory reactions and the direct engagement of muscle-expressed TLR4 by pathogen-derived molecules may synergise to induce muscular wasting in sepsis." (PMID 31959927, 2020). "This suggests that a better understanding of the attributes of C5AR1 and its interactions with C5a and the TLR4 pathways could prove useful particularly for maximizing dairy cow resilience against extreme disease outcomes such as sepsis." (PMID 33195534, 2020). "Thus, an effective blockage of macrophage activation by suppressing its TLR4/NF-κB/JNK pathways at early phage of sepsis is crucial." (PMID 32457606, 2020). "The overexpression of miR-103 may be a promising therapeutic target of sepsis by attenuating inflammatory response through the TLR4 signaling." (PMID 32455124, 2020). "In the active state of macrophages, DJ-1 probably exerts protective functions through NOX-dependent ROS production against sepsis to facilitate TLR4/MAPKs and/or TLR4/NF-κB signaling pathways, resulting in releasing pro-inflammatory mediators, killing bacteria, and polarizing to the M1 phenotype." (PMID 32612601, 2020). "Therefore, we cannot predict the effects of TLR4 inhibition on sepsis when the infection and systemic inflammatory response is ongoing." (PMID 31959927, 2020). "The TLR4 antagonist Eritoran (E5564) reached Phase III clinical trials for the treatment of sepsis." (PMID 33679711, 2020). "In the present study, we found that the TLR4/NF-κB signaling pathway was activated during sepsis." (PMID 32908632, 2020). "In humans, a non-functional variant of TLR4 (D229G) had no impact on the development or the outcome of polymicrobial sepsis in homozygous and heterozygous individuals." (PMID 33336149, 2020). "Furthermore, TLR4 was indicated to regulate the expression levels of inflammatory proteins and inflammatory cytokines in a model of LPS-induced murine sepsis." (PMID 33123130, 2020). "We found that exposure of human endothelial cells to LPS/PepG resulted in mitochondrial dysfunction and oxidative stress, associated with changes in expression of genes and selected proteins involved in TLR2 and TLR4 signalling and the inflammatory response to conditions of sepsis." (PMID 32110961, 2020). "The deficiency of toll-like receptor 4 (TLR4) in mice has demonstrated the key role of this receptor for full tissue injury in AP, while its involvement in AP-associated acute lung injury appears to be important only when the disease is worsened by sepsis." (PMID 32751171, 2020). "TLR4 inhibition by small molecules and antibodies could therefore provide access to innovative therapeutics targeting sepsis as well as acute and chronic inflammations." (PMID 32765484, 2020).